RNU6-332P (RNA, U6 small nuclear 332, pseudogene)
Gene: Small nuclear RNA gene on chromosome X (94,003,815 to 94,003,922, reverse strand). Ensembl gene ENSG00000212495.
Homologues: Orthologues: chimpanzee U6 (99% identical), macaque U6 (95% identical), pig U6 (82% identical). Paralogues in human: RNU6-774P (81% identical), RNU6-1309P (81% identical), RNU6-200P (81% identical), RNU6-936P (81% identical), RNU6-116P (80% identical), RNU6-1322P (80% identical), RNU6-742P (80% identical), RNU6-1158P (79% identical), RNU6-21P (79% identical), RNU6-652P (79% identical), RNU6-657P (79% identical), RNU6-767P (79% identical), and 1284 more.